EBF3 (EBF transcription factor 3)
Diseases named in the same sentence as EBF3 in open-access papers (continued):
Sharing a sentence is not in itself a finding about the gene and the disease.
metastatic melanoma (3 papers, 2017 to 2024). A melanoma that has spread from its primary site to another anatomic site. "Our previous findings suggested that high EBF3 expression is associated with high EBF3 promoter methylation in metastatic melanoma cell lines." (PMID 38473261, 2024). "Taken together, these data suggest that EBF3 expression is associated with aggressive phenotypic behavior in metastatic melanoma cell lines." (PMID 28030832, 2017). "Taken together, these results suggest that high EBF3 promoter methylation is associated with higher levels of EBF3 expression in metastatic melanomas." (PMID 28030832, 2017). "We found that hypermethylation of the EBF3 promoter was associated with increased EBF3 mRNA levels in metastatic melanomas and subsequent inhibition of DNA methylation reduced EBF3 expression." (PMID 28030832, 2017). "Relatively greater hypomethylation in the EBF3 gene body was observed in metastatic melanoma and colorectal cancer vs primary, in both tumour tissues and cell lines." (PMID 31383000, 2019). "Characteristic DNA methylation differences have been identified between primary and metastatic melanomas at EBF3 and/or TBC1D16 gene loci." (PMID 31383000, 2019). "To confirm the RRBS results, which showed hypermethylated fragments in the EBF3 promoter in metastatic melanoma cell lines, we performed locus specific bisulfite cloning and sequencing in four cell lines (Mel-ST, WM115, WM266-4 and Hs688(A).T)." (PMID 28030832, 2017). "RNAi-mediated knockdown of EBF3 mRNA levels decreased proliferation, migration and invasion in primary and metastatic melanoma cell lines." (PMID 28030832, 2017). "EBF3 knockdown in our functional studies was associated with reduced MTT values, migration and/or invasion in half (4 of the 8) of the metastatic melanoma cell lines investigated (WM115, WM266-4, NZM6, NZM9, NZM40)." (PMID 28030832, 2017). "We hypothesize that transcriptional repression is abrogated by the EBF3 promoter methylation, leading to elevated EBF3 expression in metastatic melanoma." (PMID 28030832, 2017). "The promoter of EBF3 was hypermethylated in all three metastatic melanoma cell lines." (PMID 28030832, 2017).
metastatic tumors (3 papers, 2017 to 2022). "Hypomethylation of EBF3 were observed in a number of metastatic tumors." (PMID 35757013, 2022).
acute myeloid leukemia (2 papers, 2015 to 2024). Acute myeloid leukemia (AML) is a group of neoplasms arising from precursor cells committed to the myeloid cell-line differentiation. "It inhibits ferroptosis in TSCC cells by inhibiting miR-125b-5p and enhancing SLC7A11, while in acute myeloid leukemia (AML), muscle ARNT-Like protein-1 (Bmal1) prevented RSL3-induced ferroptosis through EZH2-mediated EBF3 methylation to inhibit the expression of EBF3 and ALOX15." (PMID 39518098, 2024).
gastric carcinoma (2 papers, 2015 to 2021). A carcinoma that arises from epithelial cells of the stomach. "In gastric carcinoma, inactivation of the EBF3 gene is frequently accompanied by promoter hypermethylation in several gastric cancer cell lines." (PMID 25609158, 2015). "Kim and coworkers showed that EBF3, a tumor suppressor gene, was methylated in gastric carcinoma and its function could be restored with 5-Aza-dC treatment." (PMID 33854627, 2021). "Promoter methylation of EBF3 was detected in 42/104 (40.4%) gastric cancer tissues but not in normal gastric tissues." (PMID 25609158, 2015).
glioblastoma (2 papers, 2015 to 2019). The most malignant astrocytic tumor (WHO grade IV). "The epigenetic silencing of the EBF3 locus is very frequent in glioblastoma." (PMID 25609158, 2015). "Epigenetic silencing and genomic deletion of the EBF3 locus on chromosome 10q are very frequent in glioblastoma (GBM)." (PMID 25609158, 2015).
glioma (2 papers, 2019 to 2021). A benign or malignant brain and spinal cord tumor that arises from glial cells (astrocytes, oligodendrocytes, ependymal cells). "Hypomethylation in the EBF3 gene body was also observed in squamous cell carcinoma of the lung, adenocarcinoma of the lung, glioma and in colorectal cancer tissue or cell lines in comparison to normal colon tissues or cell lines." (PMID 31383000, 2019). "Because the heightened expression or non-expression of MGMT plays a pivotal role in glioma therapeutics, we applied bioinformatics and experimental tools to identify the regulatory elements in the MGMT and neighboring EBF3 gene loci." (PMID 33801310, 2021).
hepatocellular carcinoma (2 papers, 2017 to 2021). A malignant tumor that arises from hepatocytes. "In addition, forced expression of EBF3 in medulloblastoma cancer stem cells, or in HepG2 hepatocellular carcinoma cells was associated with enhanced tumorigenesis, or increased cell cycling, respectively." (PMID 28030832, 2017).
osteosclerosis (2 papers, 2022 to 2023). Abnormally high bone density. "Interestingly, Ebf3 deletion in LepR-Cre-expressing or Prx1-Cre-expressing cells led to osteosclerosis and HSCs depletion, indicating the important role of Ebf3 in maintaining stemness and HSCs niches." (PMID 36261411, 2022).
adenoma (1 paper, 2019). A neoplasm arising from the epithelium. "In liver metastases, there was further 15% loss of methylation at several EBF3 gene body sites compared to carcinomas (magenta vs green boxplots), and 19% loss of methylation compared to adenomas (magenta vs red boxplots)." (PMID 31383000, 2019). "Almost all analysed CpG sites in EBF3 and TBC1D16 were significantly differentially methylated (− 14% in the gene body of EBF3 and + 9% in the gene body of TBC1D16) in both adenomas and carcinomas compared to normal colon tissue (red vs blue and green vs blue boxplots, respectively)." (PMID 31383000, 2019).
adrenal tumors (1 paper, 2022). "They assessed in the perirenal region of PPGL higher expression of UCP1, CIDEA, ELOVL3, EBF3, FBXO31 and LHX8, but not TNFSRF9, TBX1 or TMEM26, in comparison with seven subjects with non-functional adrenal tumors." (PMID 35327387, 2022).
autism spectrum disorder (1 paper, 2025). A spectrum of developmental disorders that includes autism, and Asperger syndrome. "We focused on the hs737 enhancer of EBF3, a region where several independent rare variants have been identified in patients with autism spectrum disorder and intellectual disability." (PMID 39762235, 2025).
B-cell chronic lymphocytic leukemia (1 paper, 2022). "miR-650 on chromosome 22 is located in the Ig λ light chain locus (IgL) and increased expression in B cell chronic lymphocytic leukemia (B-CLL) predicts a more favorable disease course and targets CDK1, ING4 and EBF3." (PMID 35202088, 2022).
cleft palate (1 paper, 2023). Cleft palate is a fissure type embryopathy that affects the soft and hard palate to varying degrees. "This suggests that the rate of cleft palate among individuals with putatively causative sequence variants in EBF3 is approximately 20% (3/15; 95% confidence interval (CI) = 4.3–48.1%)." (PMID 37532691, 2023). "This subcluster is likely to be from the upper palate based on RUNX1 expression and could explain how EBF3 is a risk factor for cleft palate." (PMID 37532691, 2023).
colon carcinoma (1 paper, 2016). "Expression of Ebf3 was previously shown to promote cell cycle arrest and apoptosis in several tumor cell lines including colon carcinoma." (PMID 27092172, 2016).
colorectal cancer (1 paper, 2019). A primary or metastatic malignant neoplasm that affects the colon or rectum. "We also evaluated methylation changes of EBF3 and TBC1D16 in 450k methylation array and RRBS datasets of colorectal cancer." (PMID 31383000, 2019).
cutaneous melanoma (1 paper, 2019). A primary melanoma arising from atypical melanocytes in the skin. "From this study, a mutational landscape of cutaneous and ocular melanoma, and implicated Early B Cell Factor 3 (EBF3) as a potential cutaneous melanoma pre-deposition gene." (PMID 30809243, 2019).
endometrial cancer (1 paper, 2019). Primary or metastatic malignant neoplasm involving the endometrium (mucous membrane that lines the endometrial cavity). "In endometrial cancer, CpG sites in the gene bodies of EBF3 (cg09649486, cg25866634) and TBC1D16 (cg07618085) were significantly differentially methylated (+ 17% and − 14%, respectively) in lymph node metastases compared to primary tumours (green vs red boxplots)." (PMID 31383000, 2019).
endometrial tumours (1 paper, 2019). "Furthermore, three EBF3 gene body CpG sites (cg09649486, cg25866634, cg03774288) showed a 19% gain of methylation in endometrial hyperplasia compared to primary endometrial tumours (blue vs red boxplots)." (PMID 31383000, 2019).
hereditary ataxia (1 paper, 2021). An instance of an atactic disorder that is caused by an inherited genomic modification in an individual. "These diagnoses included a de novo EBF3 missense variant in a patient with hereditary ataxia." (PMID 34758253, 2021).
Hypertension (1 paper, 2018). The presence of chronic increased pressure in the systemic arterial system. "The result showed that miR-124a might be involved in the pathogenesis of hypertension via targeting Ebf3 and Rgs7bp, which possibly serves as a novel and effective strategy for the treatment of hypertension." (PMID 30648107, 2018).
leukemia (1 paper, 2015). A malignant (clonal) hematologic disorder, involving hematopoietic stem cells and characterized by the presence of primitive or atypical myeloid or lymphoid cells in the bone marrow and the blood. "EBF3 promoter was hypermethylated in 10/12 leukemia cell lines." (PMID 25609158, 2015).
metastatic cancers (1 paper, 2019). A carcinoma which has spread from the original site of growth to another anatomic site. "Molecular signatures of these circulating tumour cells (CTCs), such as the methylation status of EBF3 and TBC1D16, could potentially be used as a biomarker to help determine the prognosis of metastatic cancers." (PMID 31383000, 2019).
neuroblastoma (1 paper, 2021). Neuroblastoma (NB) is the most common solid, extracranial childhood tumor. "To assess the global transcriptional control of EBF3, we analyzed its genome-wide bonding profile from chromatin immunoprecipitation sequencing (ChIP-seq) in the human neuroblastoma cell line SK-N-SH." (PMID 34256850, 2021).
orofacial clefting (1 paper, 2023). "Our multi-layered analyses implicated EBF3 as an important player in gene regulation during human craniofacial development and a risk factor for orofacial clefting." (PMID 37532691, 2023). "To explore this prediction, we examined the EBF3 locus chromatin architecture, GWAS associations for orofacial clefting, phenotype data from haploinsufficient individuals, and cell-specific expression in both human and mouse." (PMID 37532691, 2023). "This is consistent with our genetic findings above of EBF3 being a risk factor for orofacial clefting in humans." (PMID 37532691, 2023). "To further determine if haploinsufficiency EBF3 is associated with an elevated occurrence of orofacial clefting, we examined the DECIPHER124 database for individuals with copy number variants (CNVs) encompassing this gene." (PMID 37532691, 2023).
osteoporosis (1 paper, 2022). A condition of reduced bone mass, with decreased cortical thickness and a decrease in the number and size of the trabeculae of cancellous bone (but normal chemical composition), resulting in increased fracture incidence. "Furthermore, we revealed that transcription factor EBF3 could directly bind the promoter site of LINC01119, which could provide novel insights for future exploration of osteogenic differentiation and osteoporosis." (PMID 35093173, 2022).
osteosarcoma (1 paper, 2022). A usually aggressive malignant bone-forming mesenchymal neoplasm, predominantly affecting adolescents and young adults. "In this study, we show the abundant expression of the CAR cell–associated surface marker LEPR, and the characteristic transcription factor associated with CAR cells, EBF3, in a subset of human osteosarcoma samples." (PMID 35309866, 2022). "Fifteen cases of primary osteosarcoma were analyzed for established markers associated with CAR cells (LEPR, EBF3, CXCL12, PDGFRA) and subdivided into low‐grade parosteal (7/16) or high‐grade intramedullary (9/16) tumors." (PMID 35309866, 2022). "Here, we analyze osteosarcomas via immunohistochemistry for known markers of CAR cells such as leptin receptor (LEPR), B‐cell factor 3 (EBF3), CXCL12, and platelet‐derived growth factor receptor alpha (PDGFRA)." (PMID 35309866, 2022). "EBF3 and LEPR followed the same expression pattern across low‐ and high‐grade tumors with nearly all LEPR+ osteosarcomas (6/8) also expressing EBF3." (PMID 35309866, 2022).
pancreatic ductal adenocarcinoma (1 paper, 2015). An infiltrating adenocarcinoma that arises from the epithelial cells of the pancreas. "Cancer-specific somatic mutations were detected of EBF3 in GBM and both EBF1 and EBF3 in pancreatic ductal adenocarcinoma." (PMID 25609158, 2015).
Parkinson disease (1 paper, 2025). A progressive degenerative disorder of the central nervous system characterized by loss of dopamine producing neurons in the substantia nigra and the presence of Lewy bodies in the substantia nigra and locus coeruleus. "Interestingly, GSEA also indicated LCNM+-enriched expression of genes that are regulated by several TFs—ATF4, EBF3, STAT3, and MEF2D—all of which are protective against Parkinson’s disease, or associated with NM content in dopamine cells of the substantia nigra." (PMID 41278831, 2025).
phaeochromocytoma (1 paper, 2017). "An oncogenic role for EBF3 has been reported in several other cancer types, including elevated expression of EBF3 in phaeochromocytoma." (PMID 28030832, 2017).
pituitary tumor (1 paper, 2024). A benign or malignant neoplasm affecting the pituitary gland. "This study suggests EBF3’s potential oncogenic effects in GH-secreting pituitary tumors." (PMID 39139281, 2024).
prostate carcinoma (1 paper, 2019). A carcinoma that arises from epithelial cells of the prostate gland. "In prostate cancer metastases significant hypermethylation of one EBF3 (cg03774288) gene body CpG and four TBC1D16 (cg07618085, cg17295878, cg23651872, cg19004465) CpG sites (both + 16%) were observed compared to normal prostate tissue (red vs blue boxplots)." (PMID 31383000, 2019).
respiratory failure (1 paper, 2021). The significant impairment of gas exchange within the lungs resulting in hypoxia, hypercarbia, or both, to the extent that organ tissue perfusion is severely compromised. "Ebf3-deficient mice reportedly died of respiratory failure due to diaphragmatic relaxation dysfunction within 12 h postpartum." (PMID 34367240, 2021).
retinoblastoma (1 paper, 2025). A malignant tumor that originates in the nuclear layer of the retina. "Interestingly, the level of expression of UBE2C, EBF3, GAP43, and PDC was reminiscent of a profile of non-proliferative subtype 1 retinoblastoma (cluster 1 population), also cited in previous studies as cone precursors and cone precursor-like." (PMID 40898088, 2025).
trisomy 21 (1 paper, 2023). A chromosomal disorder consisting of the presence of an extra chromosome 21. "Methylation of members of this gene family have been associated with a number of phenotypes, including EBF4 methylation associated with hematopoiesis and neuronal development in persons with Trisomy 21, and EBF1 and EBF3 methylation to neurobehavioral development in very preterm infants." (PMID 36959629, 2023).
tumor (20 papers, 2009 to 2025). "Furthermore, STF reversed the effects of IL-1β on downregulation of various genes, such as, EBF3 associated with B lymphocyte differentiation, bone and neuronal genesis and tumor suppression." (PMID 28068976, 2017). "Therefore, EBF3 regulates a transcriptional program underlying a putative tumor suppression pathway." (PMID 25609158, 2015). "EBF3 directly activated p21 and p27 gene transcription and inhibited tumor cell proliferation through cell cycle blockade and apoptosis." (PMID 40264043, 2025). "A recent study has revealed a potential relationship between AIFM2 and EBF3, which acts as a tumor suppressor gene in AML." (PMID 36338716, 2022). "All cells from clusters 0 and 2 (CRX+/EBF3+/GAP43+ tumor cells), and some cluster 3 cells, corresponded to the first profile (multiple alterations)." (PMID 34552068, 2021). "The CRX+/EBF3+/GAP43+ tumor population (clusters 0 and 2), presenting numerous genomic alterations, appeared to be genomically homogeneous." (PMID 34552068, 2021). "There were also four CpG sites in the EBF3 promoter that were hypermethylated + 30% in primary tumours of the colon compared to normal colon (magenta vs blue boxplots)." (PMID 31383000, 2019). "The EBF3 gene body was comparatively highly methylated on average in all of the tumour samples (median = 0.75)." (PMID 31383000, 2019). "The present findings suggest that methylation changes in EBF3 and TBC1D16, similar to those reported previously, are found in multiple different tumour types and are associated with aggressive tumour behaviour." (PMID 31383000, 2019). "We show here that in several cancer types, characteristic methylation changes in both EBF3 and TBC1D16 were associated with tumour metastasis, which is responsible for the majority of cancer-related deaths." (PMID 31383000, 2019). "In a genome-wide screen for putative tumor suppressor genes, the EBF3 locus on the human chromosome 10q26.3 was found to be deleted or methylated in 73% of brain tumor cases." (PMID 25609158, 2015). "EBF3 is a transcription factor reported to be a tumor suppressor gene with observed silencing in CRC cell line HCT116, was bivalent in normal and lost both marks in tumor." (PMID 22011431, 2011). "EBF3 is expressed in the developing central nervous system (CNS) and adult brain and recent evidence suggests it acts as a tumour suppressor." (PMID 20011110, 2009). "EBF3 has been the subject of several studies in tumor cells." (PMID 40264043, 2025). "EBF3 has a role in neurogenesis, and it has also been shown to have tumor suppressor activity." (PMID 38499326, 2024). "Also, in multiple tumor cell lines, the transcription factor ebf3, which is essential for metastasis, exhibits paradoxical hyper-methylation in its promoter during gene activation." (PMID 34979916, 2022). "Moreover, we also observed the decreased tendency of the DNA methylation β-value of EBF3-cg26229752 in the advanced tumor stage (P=0.6)." (PMID 34100918, 2021). "EBF3 encodes a member of the early B-cell factor (EBF) family of DNA binding transcription factors, and may function as a tumor suppressor in several types of cancer." (PMID 33081725, 2020). "Silencing of the EBF3 locus has been observed in brain, colorectal, breast, liver, and bone tumor cell lines, and its reactivation was achieved with 5-aza-2′-deoxycytidine and trichostatin A treatment in a significant portion of these tumor cells." (PMID 25609158, 2015). "To further evaluate whether these epigenetic changes may act more generally as drivers of tumour onset and metastasis, we have investigated DNA methylation changes involving EBF3 and TBC1D16 in additional publicly available data of multiple different tumour types." (PMID 31383000, 2019). "Therefore EBF3 has previously been postulated to be a tumor suppressor gene." (PMID 28030832, 2017).